TNFRSF14 (TNF receptor superfamily member 14)
Diseases named in the same sentence as TNFRSF14 in open-access papers (continued):
Sharing a sentence is not in itself a finding about the gene and the disease.
tumor (continued). "Chronic-IFN-γ-treatment of tumour cells induced STAT1-associated epigenomic changes, promoting IFN-γ-independent expression of ISGs including ligands for multiple TCIRs, such as TNF receptor superfamily member 14 (TNFRSF-14) and MHC-II, that conferred resistance to ICBT in preclinical models." (PMID 37503572, 2023). "PD-L1 and TNFRSF14 inactivation in malignant B-cells may eliminate their inhibitory regulation to T-helper cells, indirectly enhancing their activities, and hence exaggerating their help to tumour B-cells." (PMID 34021249, 2021). "Further, expression of lymphotoxin-A and tumor necrosis factor superfamily-14 (TNFSF14/LIGHT) by NK and complementary TNFRSF1B and TNFRSF14/HVEM (herpes virus entry mediator) by CTL may serve as a substrate for CTL–NK compartmentalization in tumors or tumor-draining lymph nodes." (PMID 31456803, 2019). "The ligand of BTLA is Herpes Virus Entry Mediator (HVEM, or TNFRSF14, is a TNF‐receptor family member), which is up‐regulated in various tumours." (PMID 40415479, 2025). "Furthermore, the reduced proliferation, migration and invasion of tumor cells induced by TNFRSF14 knockdown were partly restored by FAK wild type or p65 wild type vector transfection in these cells, which couldn’t be obtained by the transfection of FAK Y397F mutant and NLS mutant vectors." (PMID 39085878, 2024). "Among immunostimulators, CD276, PVR, TNFRSF14, TNFRSF25 and TNFSF9 were also negatively correlated with LAMP3 expression in some tumours." (PMID 38146591, 2024). "The expression of ligands, including TNFRSF14, CD274, and LGALS9, on tumor cells increased in the LN-out group." (PMID 38519500, 2024). "For example, acting as a receptor for TNFSF14 or LTA, TNFRSF14 can stimulate downstream NF-κB signaling to promote NK cell and T-lymphocyte proliferation, IFN-γ production, and tumor cell clearance." (PMID 34858395, 2021). "Immune checkpoints expressed in tumor cells, including PD-L1 (CD274), galectin 9 (LGALS9), HVEM (TNFRSF14), exhaust CD8+ T cells and reduce CD8+ T-derived cytotoxicity." (PMID 34685495, 2021). "It was found that the risk score had negative correlation with the BTLA, CD27, CD40, CD80, and TNFRSF14 expression, which had significant differences in different risk groups, indicating that tumor immunosuppression might lead to an increased risk score of patients." (PMID 34899848, 2021). "The TNFR superfamily proteins are expressed by antigen-presenting cells (APC) or tumor cells, including TNFSF4 (OX40L), TNFRSF5 (CD40), TNFSF7 (CD70), TNFSF9 (CD137L), TNFRSF14 (HVEM), and TNFSF18 (GITRL)." (PMID 30609841, 2019). "To examine this possibility, we collected a confirmed list of immunosuppressive genes and found a positive correlation between p62 and the main suppressors of T-cell immune function on the tumor cell surface, including EBAG9, PVR, B7-H3, TNFRSF14, TGFB1, and PD-L1, in most cancers." (PMID 41291343, 2025). "For instance, the activation of LIGHT production by NK cells has been observed in tumor-sensing NK cells, leading to the priming of novel antitumor responses through the interaction of NK-derived LIGHT with its receptor, HVEM (Tnfrsf14), on the surface of dendritic cells." (PMID 39768135, 2024). "Interestingly, we observed marked upregulation of a series of immune checkpoints (e.g., CD86, CD80, HAVCR2 and LGALS9) in most tumor infiltrating myeloid cells, and a unique pattern in TAMs (e.g., NECTIN2, TNFRSF14, CD276 and TNFRSF9)." (PMID 38414027, 2024). "The qRT-PCR results showed that CXCL1, PIGR, and TNFRSF14 were significantly lower expressed in BC tissues than adjacent tissue, while CXCL13 and NKAIN were significantly upregulated in BC tissues compared with adjacent tumor tissue." (PMID 39287311, 2024). "IHC analysis also confirmed that anti-TNFRSF14 treatment exactly reduced the expression of TNFRSF14 in mice GBM tumor, no matter compared with control group or PD-L1 blockade group." (PMID 39085878, 2024).
tumor (continued). "Moreover, the expression of ADAM10 was reciprocally exclusive with some tumor immune checkpoint genes, such as VEGFB, LAG3, IL4, TNFRSF18, TNFRSF4, TNF receptor superfamily member 14 (TNFRSF14), CD27, CCL5, etc.." (PMID 39211038, 2024). "Given their expression of PVR, TNFRSF14 and CD80/CD86, they might be under direct control by TIGIT+CTLA4+CSF2+TNFSF14+ tumor cells." (PMID 33968070, 2021). "While anti-PD-L1 treatment induced compensatory TNFRSF14 elevation by IFN-γ production in mouse GBM tumor, we sought to examine in vivo efficiency of TNFRSF14 inhibition and its combination with PD-L1 blockade on tumor growth in mouse immune competent orthotopic GBM model." (PMID 39085878, 2024). "Besides, MIF-EGFR/TNFRSF14, IGF1/2-IGF1R/2 R, TNFSF12-TNFRSF12A (TWEAK-Fn14) interactions also mediated the crosstalk between TPF or SLF with EPCs, consistent with their function in facilitating tumor progression." (PMID 36198671, 2022). "By immunohistochemical detection of MYH11, TNFRSF14, and Ki67 expression in harvested xenograft tumors, we observed a significant increase in MYH11 expression and a significant decrease in Ki67 and TNFRSF14 expression in tumor tissues from the mice injected with cells overexpressing MYH11." (PMID 34380460, 2021). "The results showed that the risk scores were negatively associated with the expression of the critical immune checkpoints (TNFRSF14 and CD40), indicating that the poor prognosis of high IGPM patients might be due to the tumor immunosuppressive microenvironment." (PMID 33628738, 2020). "In contrast, CDH18 showed negative correlations with TNFSF14, TNFSF15, PDCD1, TNFRSF14, and CD44, genes reported to play critical roles in tumor inhibition." (PMID 40017628, 2025). "We found that tumor purity was only negatively related to three immune genes, namely, CD8A (R = −0.18, p = 1.06 e-06), CXCR2 (R = −0.18, p = 2.90 e-07), and TNFRSF14 (R = −0.21, p = 2.58 e-09), but not to other immune-related genes, including the well-known PD1, PD-L1, and CTLA4." (PMID 34925437, 2021). "Although Tnfrsf14 knockdown in ID8 cells did not alter the frequency of CD8+ T cells or CD8+ TEM in the ascites, the robust elevation in the number of cytotoxic T lymphocytes (CTLs, IFNγ‐producing CD8+ T cells) in Tnfrsf14KD‐ID8 tumor‐bearing mice indicates enhanced antitumor immunity." (PMID 40105652, 2025). "It has been indicated that TNFRSF14 may interact with FAK, a non-receptor tyrosine protein kinase, which is well-known for its role in tumor initiation and progression and promoting the survival and immune evasion of cancer cells through kinase-dependent and kinase-independent mechanisms." (PMID 39085878, 2024).
cancer (105 papers, 2014 to 2026). A tumor composed of atypical neoplastic, often pleomorphic cells that invade other tissues. "Six of these—CD5, CTLA4, TIGIT, LAIR1, PDCD1, and TNFRSF14—encode proteins that have been identified as immune checkpoints, defined broadly as receptors on immune cells that are exploited by cancer cells to escape the immune response." (PMID 39887658, 2025). "In particular, the association between TNFRSF14 and cancer cell IFN-γ signaling activation and the cell populations in which TNFRSF14 exerts biological effect in GBM remains to be further clarified." (PMID 39085878, 2024). "Specifically, several immune checkpoints including TNFRSF18, TNFRSF4, VSIR, LGALS9, HAVCR2, and TNFRSF14 are significantly associated with RARA-AS1 in more than 10 types of cancer." (PMID 37833349, 2023). "Our data demonstrated that the knockdown of Tnfrsf14 in the murine OvCa cell line ID8 inhibited cancer cell proliferation in vitro under normoxic conditions." (PMID 40105652, 2025). "Our data revealed that decreased expression of TNFRSF14/HVEM in ID8 cells significantly inhibited cancer cell growth." (PMID 40105652, 2025). "Altogether, these data indicate a cancer intrinsic TNFRSF14 signaling cascade in GBM cells, in which TNFRSF14 directly phosphorylates FAK at Y397 and thereby affects p65 nuclear translocation." (PMID 39085878, 2024). "Collectively, these data suggest a promoting role of cancer intrinsic TNFRSF14 on the tumorgenicity of GBM cells." (PMID 39085878, 2024). "Ablating cancer intrinsic TNFRSF14 alters TME constitution with elevated perforin expression and more CD8+ T cell infiltration accompanying with less anti-inflammatory macrophages." (PMID 39085878, 2024). "Our study highlights a novel resistant mechanism to IFN exposure and PD-L1 blockade in cancer: Malignant cells under IFN-γ exposure in TME acquire intrinsic TNFRSF14 elevation, which leads to resistance to ICB." (PMID 39085878, 2024). "We employed mouse immune competent orthotopic GBM cell transplantation model to characterize TME remodeled by cancer intrinsic TNFRSF14 in GBM." (PMID 39085878, 2024). "Immunofluorescence analysis in clinical GBM samples demonstrated that there were malignant cells with co-staining of TNFRSF14 and GFAP, indicating cancer intrinsic TNFRSF14 expression in GBM." (PMID 39085878, 2024). "Given the driving role of malignant cells in cancer initiation and progression and the current limited understanding on cancer intrinsic IC mechanisms, we selected the functions of cancer cell intrinsic TNFRSF14 for further investigation." (PMID 39085878, 2024). "For immunomodulators, we found that the KIFscore was positively correlated with ULBP1, MICB, and CD276, while it was negatively correlated with TNFSF13 and TNFRSF14 in the vast majority of cancers." (PMID 37711200, 2023). "For cancer associated LR interactions from the immune-to-epithelial, the HGSOC patients had higher ITGA4_MDK and BTLA (to VTCN1 and TNFRSF14)." (PMID 38328306, 2023). "Concerning immune checkpoints, highly expressed TNFSF14 in Neutrophils, NK Cells, and Monocytes, BTLA in Treg Cells, Granulosa Cells, and B Cells, together with LTBR and TNFRSF14 in Cancer Cells, interact to help kill Cancer Cells." (PMID 36401283, 2022). "Aberrant expression of TNFRSF6B in cancer cells inhibited Fas-mediated and TNFRSF14-mediated apoptosis, leading the cancer cells to escape during the immune process." (PMID 33192575, 2020). "However, delving into the details of the role of TNFRSF14 in cancer biology is beyond the scope of this review." (PMID 40362653, 2025). "Finally, we confirmed that the expression levels of the top immunosuppressive genes, EBAG9, PVR, TGFB1, B7-H3, TNFRSF14, and PD-L1, were significantly higher in the high-p62 group than in the low-p62 group in most cancers." (PMID 41291343, 2025). "Therefore, the TNFRSF14-BTLA ligand–receptor pair is considered a plausible target for cancer immunotherapy." (PMID 40362653, 2025).
cancer (continued). "In addition, Defactinib, a FAK inhibitor, efficiently reduces in vitro GBM cell proliferation brought by cancer intrinsic TNFRSF14 elevation." (PMID 39085878, 2024). "Next, we sought to evaluate whether cancer intrinsic TNFRSF14 contributes to the constitution of immunosuppressive TME in GBM." (PMID 39085878, 2024). "Our findings highlight a malignant TNFRSF14/FAK axis as a potential target to blunt cancer-intrinsic resistance to ICB treatment, which may help improve the therapeutic efficiency of immunotherapy in malignancies." (PMID 39085878, 2024). "Mechanistically, cancer intrinsic TNFRSF14 phosphorylates FAK at Y397 and activates its downstream NF-κB signaling, which not only enhances the tumorigenicity of GBM cells, but promotes the recruitment of anti-inflammatory TAMs through elevating CXCL1 and CXCL5 secretion from GBM cells." (PMID 39085878, 2024). "Together, these results indicate that there is a cancer intrinsic TNFRSF14 elevation in GBM accompanying with IFN-γ signaling activation, which may be a potential compensatory mechanism to IFN-γ exposure in GBM and indicate poor prognosis of GBM patients." (PMID 39085878, 2024). "After observing the functional role of FAK/ FAK Y397 phosphorylation induced by cancer intrinsic TNFRSF14 in promoting malignant progression of GBM, we sought to validate the association between FAK/ FAK Y397 phosphorylation induced by TNFRSF14 and TAMs infiltration in clinical GBM samples." (PMID 39085878, 2024). "Next, we sought to clarify the downstream effector of cancer intrinsic TNFRSF14 in GBM cells." (PMID 39085878, 2024). "Notably, VSIR, LGALS9, and TNFRSF14 are highly correlated with RARA-AS1 in 16 types of cancer, indicating their potential as therapeutic targets." (PMID 37833349, 2023). "The expression profiles of cancer-related checkpoints showed that the majority of checkpoint-target genes had low expression levels in the high-risk group, and only TNFRSF25, TNFRSF4, TNFRSF14, TNFRSF18, and CD276 were upregulated in the high-risk group." (PMID 37190215, 2023). "TNFRSF14 is expressed on a broad range of cancer cells and may activate the inflammatory response, which has implicated its role in autoimmune pathogenesis." (PMID 35432372, 2022). "Of these, the average expression of the two genes, including CD70 and PDCD1, and the 12 isoforms derived from the seven genes, including CD40, CD70, IL6, IL10, STAT1, STAT6, and TNFRSF14, were cancer immunotherapy-related genes (false discovery rate (FDR) < 0.01)." (PMID 31292525, 2019). "Specifically, in most cancer types, ESRRA positively correlates with TNFRSF14, and ESRRG with CD160." (PMID 40356747, 2025). "Meanwhile, in most cancer types, a noteworthy positive connection was observed between ESRRA and TAP1 (belonging to MHC) and TNFRSF14." (PMID 40356747, 2025). "This context-dependency also extended to molecules like TNFRSF14 (HVEM), CSF1R, and several HLA genes, which were positively correlated in cancers like COAD and LIHC but negatively correlated in ESCA, LGG, and LUSC." (PMID 41614761, 2025). "In the present study, we evaluated the expression of the immune checkpoints CD276, CD44, TNFRSF14, and VSIR across a range of cancer tissues." (PMID 40727469, 2025). "HPV-positive CC tumors exhibited epithelial cells with significant enrichment of immune checkpoint ligands (LGALS9, CD274, and TNFRSF14), whereas HPV-negative carcinomas predominantly activated the CD80/86-CTLA4 pathway." (PMID 41035636, 2025). "Here, we identify a novel cancer cell-intrinsic resistance mechanism conferring from IFN-γ signaling activation, mediated by TNFRSF14 and its downstream effector, FAK." (PMID 39085878, 2024). "Since immune checkpoint inhibitors (ICIs) have been a prominent topic in cancer treatment, the expression of eight ICIs (LAG3, HAVCR2, CD27, TNFRSF14, CTLA4, TMIGD2, TIGIT, and PDCD1LG2) were analyzed between groups in the study." (PMID 37405988, 2023).
cancer (continued). "According to the correlation analysis between SRSF3 and immune checkpoint gene expression, it can be found that SRSF3 is closely related to TNFSF14, TNFRSF14, TNFRSF25, CD276, NRP1, VSIR in a variety of malignant tumors (P <0.05)." (PMID 35494088, 2022). "Correlation analysis of FDX1 with checkpoint gene expression found a high correlation (p < 0.05) with tumor necrosis factor (TNF)–related immune genes (TNFRSF14, 15, 25) and CTLA4, PDCD1, CD274, NRP1, and VTCN1 in some kinds of cancers." (PMID 36061184, 2022). "In diverse cancer types, the correlation between OAS3 and the expression of checkpoint genes indicated a high correlation with TNF-related immune genes including TNFRSF14, TNFRSF8, TNFRSF25, TNFRSF4, TNFRSF18, TNFSF15, and TNFRSF9." (PMID 35592250, 2022). "It has been reported that the expression of APOBEC3D, TNFRSF14, and RAC2 is dysregulated and is a potential target for therapy in cancer." (PMID 36059808, 2022). "LIGHT is one of the ligands of herpes virus entry mediator (HVEM, also termed TNFRSF14), and the conjugation of two molecules facilitates anti-tumoral or pro-tumoral immunity, depending on the histological type of cancer." (PMID 34513918, 2021). "We found that in some cancers, especially in LUAD and TGCT, FH expression was significantly correlated with multiple immune checkpoint markers, such as BTLA, TNFRSF14, LAIR1, CD48, and CD28." (PMID 34737838, 2021). "The immune checkpoint B- and T-lymphocyte attenuator (BTLA/CD272) and its ligand, Herpesvirus entry mediator (HVEM/CD270/TNFRSF14), are dysregulated in cancer." (PMID 33917094, 2021). "Inspection of the analyzed gene set revealed that, among the ten most specific immune response cancer genes, five were bound to or an integral part of the plasma membrane (CD70, HLA-B, TNF, TNFRSF14, and CD79B)." (PMID 26856619, 2016). "LIGHT (TNFSF14) binds to TNFRSF14 (HVEM) and LTβR on cancer cells, promoting apoptosis." (PMID 40564222, 2025). "Correlation analysis between RFC4 and checkpoint gene expression in different types of cancers showed a high correlation with immune genes including CCL4, CCL16, HLA family genes, TNFRSF8, TNFRSF14, TNFRSF18, CD70, CD44 (p < 0.05), CD276, CX3CL1 and VGEGFA (p < 0.05)." (PMID 39031628, 2024). "Among these immunostimulators, TNFRSF25 and TNFRSF14 showed a negative coexpression in more than 10 cancers." (PMID 38655053, 2024). "scRNA-seq analysis indicated that TNFRSF14 and CD47 were highly expressed in cancer cells, suggesting that CD47 may be better therapeutic targets." (PMID 37021054, 2023). "To identify potential therapeutic targets of those cancers and immune escape, we have collected more than forty representative immune checkpoint genes, including BTLA, CD200, TNFRSF14, NRP1, LAIR1 and so on, and we evaluated the relationship between expression of COL1A1 and immune checkpoint." (PMID 35789341, 2022). "In diverse cancer types, correlation analysis between CDCA4 and checkpoint gene expression indicated a high connection (P<0.05) with TNF-related immune genes including TNFRSF8, TNFRSF14, TNFRSF18, CD70, CD44, and CD276 (B7-H3)." (PMID 35251007, 2022). "It is notable that PRDM1 seemed to positively correlated with TNFRSF14 in LGG and UVM among cancers with unfavorable prognosis, while this correlation seems weak or even negative in all cancers with favorable prognosis." (PMID 33384601, 2020). "PRDM1 positively correlated with TNFRSF14 in LGG and UVM among cancers with unfavorable prognosis; this correlation were weak or even negative in cancers with favorable prognosis." (PMID 33384601, 2020).
infection (46 papers, 2010 to 2026). The state of being infected such as from the introduction of a foreign agent such as serum, vaccine, antigenic substance or organism. "TNFRSF14 demonstrated a significant increase in mRNA and cell-surface protein expression levels over the infection course and after ex vivo TR-AM stimulation with iBALF." (PMID 41252214, 2026). "HVEM (TNFRSF14) is one of the several routes of entry used by HSV-1 to initiate infection in the host." (PMID 37738264, 2023). "Significant upregulations could be observed for the genes TNFSF10 (3.8-fold change to WT infection), TNFRSF14 (3.2-fold) and MYD88 (1.9-fold)." (PMID 38400065, 2024). "HSV-1 uses several routes of entry to initiate infection of cells including HVEM (TNFRSF14), nectin-1, nectin-2, 3-O-sulfated heparan sulfate (3-OS-HS), paired immunoglobulin-like type 2 receptor (PILRα), non-muscle myosin heavy chain IIA (NMHC-IIA), and myelin-associated glycoprotein (MAG)." (PMID 37738264, 2023). "For example, if there is only a 2-fold excess of receptors for gB (MYH9) and gD (PVRL1 plus TNFRSF14), the differential efficiency of primary infection could rise 8×, and to 64× for a further round of infection." (PMID 27981441, 2017). "TNFRSF14 and LTβR, the 2 competitive TNFSF14 receptors, followed distinct kinetics in terms of transcriptional regulation and protein expression in TR-AMs during the infection course." (PMID 41252214, 2026).